KCNA3 (potassium voltage-gated channel subfamily A member 3)
Description:
[Isoform 1]: Mediates the voltage-dependent potassium ion permeability of excitable membranes. Assuming opened or closed conformations in response to the voltage difference across the membrane, the protein forms a potassium-selective channel through which potassium ions may pass in accordance with their electrochemical gradient. [Isoform 2]: Mediates the voltage-dependent potassium ion permeability of excitable membranes. Assuming opened or closed conformations in response to the voltage difference across the membrane, the protein forms a potassium-selective channel through which potassium ions may pass in accordance with their electrochemical gradient. [Isoform 3]: Lacks voltage-gated potassium channel activity.
Synonyms: HGK5; Kv1.3; MK3; HLK3; HPCN3; RP11-284N8.3; HUKIII; PCN3
Tractability: Small molecule: an approved drug acts on it; a structure with a bound ligand is known; a high-quality ligand is known; it belongs to a druggable protein family. Antibody: UniProt places it where antibodies can reach, with high confidence; its Gene Ontology location is reachable by antibodies, with high confidence; UniProt predicts a signal peptide or a membrane-spanning region. PROTAC: ubiquitination databases record sites on it; its protein half-life has been measured; a small molecule that binds it is known.
Target class: Potassium channels; Ion channel; Voltage-gated ion channel; Voltage-gated potassium channel
Chemical probes: CHEMBL3609092, Dihydroxymethoxychalcone, PAP-1 (high quality)
Gene: Protein-coding gene on chromosome 1 (110,653,560 to 110,674,940, reverse strand). Ensembl gene ENSG00000177272.
Subcellular location: Cell membrane (Isoform 1); Cell membrane (Isoform 2); Cytoplasm, perinuclear region (Isoform 3)
Pathways (Reactome):
Neuronal System: Voltage gated Potassium channels
Gene Ontology:
Molecular function: protein binding; voltage-gated potassium channel activity; delayed rectifier potassium channel activity; voltage-gated monoatomic ion channel activity; monoatomic ion channel activity
Biological process: action potential; potassium ion transmembrane transport; potassium ion transport; monoatomic ion transport; protein homooligomerization; transmembrane transport
Cellular component: plasma membrane; axon; membrane; voltage-gated potassium channel complex; perinuclear region of cytoplasm
Genetic constraint (gnomAD): Loss-of-function variants: 18 observed, 34.3 expected, observed/expected ratio (o/e) 0.52, 90% interval 0.36 to 0.78. The upper end of that interval is the gene's LOEUF score, 0.78, which puts it in group 3 of 6, group 1 being the genes least tolerant of losing a copy. Missense variants: 587 observed, 808.8 expected, observed/expected ratio (o/e) 0.73, 90% interval 0.68 to 0.78. Synonymous variants: 324 observed, 349.18 expected, observed/expected ratio (o/e) 0.93, 90% interval 0.85 to 1.02.
Homologues: Orthologues: chimpanzee KCNA3 (99% identical), macaque KCNA3 (98% identical), pig KCNA3 (96% identical), mouse Kcna3 (89% identical), rat Kcna3 (89% identical), dog KCNA3 (87% identical), guinea pig KCNA3 (86% identical), tropical clawed frog kcna2 (77% identical). Paralogues in human: KCNA2 (67% identical), KCNA1 (65% identical), KCNA4 (61% identical), KCNA6 (60% identical), KCNA5 (59% identical), KCNA10 (52% identical), KCNA7 (52% identical), KCNC4 (32% identical), KCNC3 (32% identical), KCNC2 (32% identical), KCND1 (31% identical), KCNC1 (31% identical), and 19 more.
Diseases named in the same sentence as KCNA3 in open-access papers:
KCNA3 is named in the same sentence as 157 diseases in open-access papers, as found by Europe PMC text mining. Sharing a sentence is not in itself a finding about the gene and the disease. The quoted sentences say what the papers report.
autoimmune disease (61 papers, 2009 to 2026). A disorder resulting from loss of function or tissue destruction of an organ or multiple organs, arising from humoral or cellular immune responses of the individual to their own tissue constituents. "KV1.3 (KCNA3) and calcium-activated KCa3.1 channels are primarily responsible for K+ efflux and are important therapeutic targets in various autoimmune diseases, such as multiple sclerosis, rheumatoid arthritis, and type-1 diabetes." (PMID 39398192, 2024). "In leukocytes, KCNE4 has an important role in regulating KCNA3 (Kv1.3) to act as an inhibitor of cell proliferation, activation, apo-regulation, autoimmune diseases, and T cell proliferation and activation." (PMID 35915077, 2022). "KCNA3 has been identified as a potential target for therapy in autoimmune disease, and several strategies for inhibition have been developed in this context." (PMID 23424639, 2013).
Obesity (20 papers, 2009 to 2025). Accumulation of substantial excess body fat. "Therefore, we focused our observations on identifying a possible relation between KCNA3 and KCNA5 expression and patients’ clinical features and tumor risk factors, such as age, sex, obesity, and smoking." (PMID 36978819, 2023).
melanoma (16 papers, 2014 to 2025). A malignant, usually aggressive tumor composed of atypical, neoplastic melanocytes. "Although the reported data were controversial, it would be worth investigating these relationships in the context of melanoma, considering that KCNA3 associates with a better prognosis in this tumor type." (PMID 36978819, 2023). "Interestingly, in SKCM, a high level of KCNA3 mRNA positively correlated with the elevated infiltration of CD8+ T cells, the immune cell type most associated with a greater immune response against the tumor and considered a positive biomarker of prognosis in melanoma." (PMID 36978819, 2023).
breast carcinoma (15 papers, 2012 to 2024). "These compounds are predicted to stably interact with the MMP12, CDK4, JAK3, VEGFR2, MMP13, VEGFR1, and KCNA3 proteins, which have a role in inhibiting the growth and inducing apoptosis in breast cancer cells." (PMID 36106139, 2022). "Our analysis validated KCNA3 as hypermethylated in breast cancer, plus identified it as hypermethylated in an additional 7 tumor types." (PMID 23033966, 2012).
glioma (12 papers, 2013 to 2026). A benign or malignant brain and spinal cord tumor that arises from glial cells (astrocytes, oligodendrocytes, ependymal cells). "Furthermore, Kv1.3 (Kcna3) is found in addition to microglia, also in astrocytes, neurons of the olfactory system, and in gliomas." (PMID 34944418, 2021).
epilepsy (6 papers, 2013 to 2026). A brain disorder characterized by episodes of abnormally increased neuronal discharge resulting in transient episodes of sensory or motor neurological dysfunction, or psychic dysfunction. "Thus, the combined decreased expression of Kcna3 (Kv1.3), Kcnk9 (TASK3), Kcnn3 (SK3), Kcng3 (Kv7.3), and Kcns3 (Kv9.3) around day 8 could lead to increased chances of persistent membrane depolarization, which ultimately may lead to epilepsy." (PMID 34877936, 2021).
atherosclerosis (5 papers, 2020 to 2024). A disease characterized by the build-up of fatty material and calcium deposition in the arterial wall resulting in partial or complete occlusion of the arterial lumen. "Thus, an association has been established between several stretch-specific miR-1183 targets and cardiac remodeling, such as: KCNA3 with diabetic cardiomyopathy, MED23 with CHD, SAMSN1 with atherosclerosis, CCND1 with myocardial ischemia-reperfusion injury, and MCOLN3 with atrial fibrillation." (PMID 35805966, 2022).
lung carcinoma (5 papers, 2017 to 2025). "For this reason, a better assessment of the KCNA3 role in lung cancer should be carried out to investigate the difference in the positive prognostic role played by this ion channel in LUAD but not in LUSC." (PMID 36978819, 2023). "Among the top 15 FC-specific hypermethylated genes, the methylation of ZSCAN31, KCNA3 and CDO1 were reported to be associated with lung cancer development." (PMID 35313869, 2022).
Arthritis (4 papers, 2017 to 2019). Inflammation of a joint. "Using a CD4+ T-cell-dependent model of arthritis, Kcna3−/− rats developed disease similarly to WT rats, indicating that Kv1.3 deficiency did not compromise immune CD4+ T-cell function." (PMID 28248292, 2017).
colorectal cancer (2 papers, 2020 to 2024). A primary or metastatic malignant neoplasm that affects the colon or rectum. "Similarly, KCNA3 was shown as hypermethylated in esophageal squamous cell carcinoma, colorectal cancer or oropharyngeal squamous cell carcinoma." (PMID 39305372, 2024).
COVID-19 (2 papers, 2022 to 2023). A disease caused by infection with severe acute respiratory syndrome coronavirus 2. "RT-qPCR experiments revealed that KCNA3 expression was increased in severe COVID-19 as compared to mild COVID-19 patients and healthy controls." (PMID 37033961, 2023). "In summary, we demonstrate that KCNA3 expression correlates with disease severity, and dexamethasone decreases the upregulation of KCNA3 that is observed in severe COVID-19 to levels below that of healthy control PBMCs." (PMID 37033961, 2023). "We conducted in vitro experiments in healthy donor PBMCs to verify our findings on altered KCNA3, ORAI1, and STIM1 gene expression in dexamethasone-treated COVID-19 patients and confirmed that in vitro treatment with dexamethasone altered the abundance of these ion channel encoding genes." (PMID 37033961, 2023).
depression (2 papers, 2018 to 2025). "The expression trends of these genes showed general consistency, except for KCNA3 in depression and ZC3H12D and CYP4F2 in renal failure exhibiting opposite expression patterns." (PMID 40595897, 2025). "PPI network analysis identified 23 hub genes, including CYP4F2, KCNA3, KISS1R, LILRA5, and ZC3H12D, as key players in the shared pathophysiology of ESRD and depression." (PMID 40595897, 2025). "We discovered that the five key genes CYP4F2, KCNA3, KISS1R, LILRA5 and ZC3H12D remained different after Venn diagram overlap of DEGs across depression and renal failure datasets." (PMID 40595897, 2025). "Further, protein-protein interaction (PPI) network analysis pinpointed five central genes CYP4F2, KCNA3, KISS1R, LILRA5, and ZC3H12D as pivotal players in the shared pathophysiology of depression and renal failure." (PMID 40595897, 2025). "PPI network analysis identified CYP4F2, KCNA3, KISS1R, LILRA5, and ZC3H12D as key players in the shared pathophysiology of ESRD and depression." (PMID 40595897, 2025).
epileptic encephalopathies (2 papers, 2024 to 2025). "Additionally, KCNA3 de novo missense variants have been associated with the development of epileptic encephalopathies in humans." (PMID 41155561, 2025). "De novo variants in KCNA3 cause developmental and epileptic encephalopathy." (PMID 39590469, 2024).
esophageal cancer (2 papers, 2020 to 2024). A primary or metastatic malignant neoplasm involving the esophagus. "We then developed a blood-based methylation assay targeting OTOP2 and KCNA3 (named “IEsohunter”) for esophageal cancer noninvasive detection." (PMID 38890756, 2024). "Based on TCGA database and literature search, we analyzed the methylation of KCNA3, USP44, OPLAH and SMTN in esophageal cancer." (PMID 32266120, 2020).
esophageal squamous cell carcinoma (2 papers, 2024). Esophageal squamous cell carcinoma (ESCC) is a type of esophageal carcinoma (EC) that can affect any part of the esophagus, but is usually located in the upper or middle third. "Plasma methylated OTOP2 and KCNA3 cycle threshold (Ct) values were significantly lower in patients with esophageal squamous cell carcinoma (ESCC) than in all controls (P < 0.0001)." (PMID 38890756, 2024).
gastric adenocarcinoma (2 papers, 2023 to 2025). "While other potassium voltage-gated genes such as KCNA2, KCNA3, and KCNA5 have been investigated across various cancers—including skin melanoma, uterine corpus endometrial carcinoma, gastric adenocarcinoma, LUAD, and LUSC in-depth studies of KCNA7’s expression in cancer remain lacking." (PMID 40568194, 2025).
ovarian carcinoma (2 papers, 2022 to 2024). A malignant neoplasm originating from the surface ovarian epithelium. "KCNA3 has been identified as a key immune-related gene in ovarian cancer, and moreover, its overexpression was associated with disease stage and superior survival." (PMID 35372049, 2022).
pancreas adenocarcinomas (2 papers, 2012 to 2021). "The gene inactivation via promoter DNA methylation events in voltage gated gene Kv1.3 (KCNA3) has been previously reported in breast and pancreas adenocarcinomas." (PMID 23033966, 2012).
cervical cancer (1 paper, 2021). A primary or metastatic malignant neoplasm involving the cervix. "They identified 6 genes as the best candidate methylated biomarkers of cervical cancer progression (RGS7, LHX8, ST6GALNAC5, TBX20, KCNA3 and ZSCAN18)." (PMID 34882728, 2021).
fungal keratitis (1 paper, 2023). "We identified 60 viral genes and 327 bacterial/fungal genes with an AUC of at least 0.9, among them MATR3, CXCL9, and KCNA3 for viral keratitis, and S100A8, CXCL8, and CCL20 for bacterial/fungal keratitis." (PMID 38274739, 2023). "MATR3 (AUC = 0.95), CXCL9 (AUC = 0.95), and KCNA3 (AUC = 0.90) were among the best candidate markers for viral keratitis, and S100A8 (AUC = 1), CXCL8 (AUC = 1), and CCL20 (AUC = 1) were among the best candidates for bacterial/fungal keratitis." (PMID 38274739, 2023).
cancer (64 papers, 2012 to 2026). A tumor composed of atypical neoplastic, often pleomorphic cells that invade other tissues. "In high-grade malignancies, Potassium Voltage-Gated Channel Subfamily A Member 3 (KCNA3) is down-regulated and mostly expressed in the early stages of cancer growth." (PMID 38361095, 2024). "Regarding KCNA3 (Kv1.3), it has been demonstrated its critical role in thymocyte pre-clonal expansion and its relevance for mediating the proliferation of different cancer lines together with primary cells." (PMID 37767500, 2023). "The eight cross-cancer CpGs were annotated to genes involved in transport (KCNA3, KCNAB3 and TRAPPC1), signal transduction (AGAP3 and LIME1), microtubule assembly (FES and SHROOM1), and metal binding (FURIN and AGAP3)." (PMID 35710732, 2022). "KCNA3 inactivation via promoter hypermethylation has been found across multiple cancer types including lung, breast, pancreas, ovarian, kidney, prostate, and colon." (PMID 35313869, 2022). "KCNA3 functions in voltage-gated potassium channels, which play a variety of roles in cancer progression." (PMID 35313869, 2022). "Further downstream analysis reveals KCNA3 promoter hypermethylation in 8 out of the 10 cancers, identifying it as one of the most prevalent events in tumorigenesis and affecting various tumor types." (PMID 23033966, 2012). "Similarly, hypermethylation of SHISA3, KCNA3, NPY, and hypomethylation of NUMB, BST2, MAPK13 promoters, which have previously been implicated in other cancers, robustly separate normal and GBC-OSCC samples." (PMID 37245006, 2023). "Therefore, these compounds are predicted to inhibit growth and induce apoptosis of cancer cells through their interactions with MMP12, MMP13, CDK4, JAK3, VEGFR1, VEGFR2, and KCNA3." (PMID 36106139, 2022). "Likewise, none of the Epi‐LumB specific markers, i.e. ZNF132, TTBK1 and KCNA3 have been described as tumor suppressors and it is not clear at this point whether epigenetic inactivation of these genes represent driver events that contribute to cancer development." (PMID 25468711, 2015).
tumor (53 papers, 2012 to 2025). "Additionally, in LUAD, the expression of KCNA3 seemed to be positively associated with the infiltration of immune subtypes that promote the anti-tumor response (Monocytes, CD4+ T cells, Mast cells, Dendritic cells) and are inversely related to M2 macrophages." (PMID 36978819, 2023). "Conversely, in LUSC, where high KCNA3 expression is associated with poor prognosis, channel expression is correlated to higher pro-immune suppressive Tregs cell infiltration and a reduced presence of the anti-tumor immune cell sub-populations." (PMID 36978819, 2023). "Considering KCNA3, it is interesting to note that its expression tends to significantly decrease with tumor stage progression compared to normal tissues in both lung tumor types which it associates with patient prognosis." (PMID 36978819, 2023). "Overall, these data highlighted SKCM, UCEC, STAD, LUSC, and LUAD to be the five cancers with the highest KCNAs mutation frequency and revealed KCNA2, KCNA3, and KCNA5 to be the most expressed KCNA family genes in these tumours." (PMID 36978819, 2023). "In head and neck cancer, tumor infiltrating lymphocytes (TILs; cells that can be recruited by the tumor cells and the cytokines that they produce can help tumor cell survival) display up to a 70% reduction in functional KCNA3 channels, consequently decreasing Ca2+ entry and CD8 T cell function." (PMID 37408210, 2023). "To this end, we determined whether the expression of KCNA3 and KCNA5 correlated with tumor stage progression, age, sex, and some specific cancer risk factors." (PMID 36978819, 2023). "The expression levels of KCNA3 decreased with increasing tumor grade in stage II,III and IV." (PMID 34868239, 2021). "They discovered that Kcnn4 and Scn2a1 channels exhibited similar expression levels in both non-tumor and tumor tissues, while the Kcna3 potassium channel were significantly overexpressed in tumor tissues." (PMID 39027429, 2024). "With KCNA2, KCNA3, and KCNA5 being the most abundant transcripts of the Shaker gene family in SKCM, UCEC, STAD, LUSC, and LUAD, we compared their expression levels in both tumour and normal samples." (PMID 36978819, 2023). "It is worth mentioning that LUSC was the only tumour analysed in which the KCNA3 transcript significantly differed between the tumour and normal samples." (PMID 36978819, 2023). "Considering the correlation with immune infiltrates, we hypothesized that KCNA3 could exert a distinct immune recruitment function in the different tissues where it was expressed, thus representing an advantage or not for the tumor progression." (PMID 36978819, 2023). "Moreover, elevated KCNA3 levels were inversely correlated with the presence of dendritic cells (both active and resting), natural killers (NKs), CD4+ T cells, and mast cells, which were all able to favor recognition, antigen presentation, and killing of tumor cells." (PMID 36978819, 2023).
KCNA3 also shares sentences with these, for which no sentence is quoted: multiple sclerosis (31 papers); rheumatoid arthritis (16); psoriasis (14); type-1 diabetes (13); Alzheimer disease (12); prostate carcinoma (10); Autoimmunity (8); diabetes (8); neurological disorders (8); Parkinson disease (8); Stroke (8); experimental autoimmune encephalomyelitis (7); immune diseases (7); ischemic stroke (7); asthma (6); neurodegenerative disease (6); infection (5); lung adenocarcinoma (5); lymphoma (5); systemic lupus erythematosus (5); Anxiety (4); chronic lymphocytic leukemia (4); colon cancer (4); coronary artery disease (4); Insulin resistance (4); ischemia (4); metabolic disease (4); osteosarcoma (4); pancreas cancer (4); breast adenocarcinoma (3).
A further 105 diseases each share a sentence with KCNA3 in 3 papers or fewer.